DR1 (down-regulator of transcription 1)
Description:
The association of the DR1/DRAP1 heterodimer with TBP results in a functional repression of both activated and basal transcription of class II genes. This interaction precludes the formation of a transcription-competent complex by inhibiting the association of TFIIA and/or TFIIB with TBP. Can bind to DNA on its own. Component of the ATAC complex, a complex with histone acetyltransferase activity on histones H3 and H4.
Synonyms: NC2-beta; NC2B; NCB2; NC2
Tractability: PROTAC: ubiquitination databases record sites on it; its protein half-life has been measured.
Gene: Protein-coding gene on chromosome 1 (93,345,907 to 93,369,493, forward strand). Ensembl gene ENSG00000117505.
Subcellular location: Nucleus
Subcellular location (Human Protein Atlas): Nucleoplasm
Pathways (Reactome):
Chromatin organization: HATs acetylate histones
Gene expression (Transcription): Formation of WDR5-containing histone-modifying complexes
Gene Ontology:
Molecular function: protein binding; RNA polymerase II general transcription initiation factor activity; TBP-class protein binding; general transcription initiation factor activity; protein heterodimerization activity
Biological process: negative regulation of transcription by RNA polymerase II; regulation of cell cycle; regulation of cell division; regulation of DNA-templated transcription; regulation of transcription by RNA polymerase II; regulation of tubulin deacetylation; negative regulation of RNA polymerase II transcription preinitiation complex assembly; regulation of embryonic development; RNA polymerase II preinitiation complex assembly
Cellular component: ATAC complex; negative cofactor 2 complex; nucleoplasm; RNA polymerase II transcription regulator complex; mitotic spindle; nucleus
Genetic constraint (gnomAD): Loss-of-function variants: 7 observed, 20.25 expected, observed/expected ratio (o/e) 0.35, 90% interval 0.2 to 0.65. The upper end of that interval is the gene's LOEUF score, 0.65, which puts it in group 2 of 6, group 1 being the genes least tolerant of losing a copy. Missense variants: 98 observed, 210.32 expected, observed/expected ratio (o/e) 0.47, 90% interval 0.4 to 0.55. Synonymous variants: 76 observed, 76.22 expected, observed/expected ratio (o/e) 1, 90% interval 0.83 to 1.21.
Homologues: Orthologues: chimpanzee DR1 (100% identical), rabbit DR1 (100% identical), dog DR1 (99% identical), mouse Dr1 (99% identical), rat Dr1 (99% identical), guinea pig DR1 (99% identical), pig DR1 (99% identical), tropical clawed frog dr1 (97% identical), zebrafish dr1 (94% identical), Drosophila melanogaster NC2beta (60% identical), Caenorhabditis elegans dro-1 (41% identical). Paralogues in human: NFYB (30% identical), FAM47E (12% identical).
Diseases named in the same sentence as DR1 in open-access papers:
DR1 is named in the same sentence as 40 diseases in open-access papers, as found by Europe PMC text mining. Sharing a sentence is not in itself a finding about the gene and the disease. The quoted sentences say what the papers report.
melanoma (5 papers, 2012 to 2023). A malignant, usually aggressive tumor composed of atypical, neoplastic melanocytes. "Intriguingly, suppression of STAT3 signaling with DR-1-55 in HLA-G OE BMICs caused a drastic decline in the secondary sphere formation of HLA-G OE lung and melanoma BMICs despite the presence of high HLA-G levels in these cells." (PMID 36780531, 2023). "In our previous studies, the B16/murine MHC knockout/HHDII+/DR1+ murine melanoma cell line was shown to constitutively express the murine WT1 protein (data not shown)." (PMID 34262856, 2021). "Therefore, melanoma resistance is probably based upon lower expression of functional death receptors (DR1 and DR2)." (PMID 25428727, 2014). "Similarly, the DR1-restricted T cell clone 5F9 also recognized one of the DRß1*0101 melanoma cell line, in the absence of exogenous peptide (M101)." (PMID 23284752, 2012).
rheumatoid arthritis (5 papers, 2008 to 2023). A chronic, systemic autoimmune disorder characterized by inflammation in the synovial membranes and articular surfaces. "For example, rheumatoid arthritis is associated with certain DR1 allotypes (in our data set, DRB1*01:01, DRB1*01:02, DRB1*04:01 and DRB1*04:04) characterized by polymorphisms in the P4 pocket." (PMID 37142807, 2023). "Rheumatoid arthritis (RA) is an autoimmune disease in which susceptibility is associated with expression of several HLA-DR alleles, including DR1 (DRB1*01:01) and DR4 (DRB1*04:01, *04:04, *04:05, and *04:08)." (PMID 33465118, 2021). "Type II collagen is a DR4/DR1 restricted target of self-reactive T cells that sustain rheumatoid arthritis." (PMID 19014626, 2008). "Therefore, in 96-well plate wells, MBP83-99 was allowed to bind to DR1 or DR15 on 3T3 cells in competition with a test compound, and the HLA-bound peptide was detected by streptavidin-conjugated β-galactosidase, thereby identifying inhibitor compounds for rheumatoid arthritis or multiple sclerosis." (PMID 28754892, 2017).
Arthritis (4 papers, 2006 to 2021). Inflammation of a joint. "Moreover, oral therapy with active forms of vitamin D suppressed arthritis in LAIR-1 sufficient DR1 mice, but were ineffective in LAIR-1−/− deficient mice." (PMID 34948139, 2021). "Using this model, we have confirmed that activation of a large number of DR1-restricted autoimmune CD4+ T cells enhances the severity of the arthritis, and this phenomenon is associated with both increased numbers of autoantibodies and enhanced levels of inflammatory cytokines." (PMID 24405551, 2014). "Treatment of the DR1 Tg mice with FTY720 resulted in a dose-dependent inhibition of the incidence and severity of arthritis concomitant with a reduced production of pathogenic CII-specific antibody." (PMID 26757712, 2016). "Previously, we identified a synthetic analog peptide of human CII, CII256–276 (F263N, E266D), also called A12, which could profoundly suppress arthritis when administered to DR1 transgenic mice." (PMID 16982003, 2006). "Considering that both DR1 and DR4 transgenic mice react with a common core epitope, it was of interest to determine whether the analog peptide A12 could also suppress arthritis in the context of DRB1*0401." (PMID 16982003, 2006). "Because FTY720 has a strong effect on CD4+ T-cell recirculation, and because collagen-induced arthritis is mediated by CII-specific CD4+ T cells, we investigated how FTY720 affected the development of the CD4+ CII-specific autoimmune T-cell response in the DR1 Tg mice." (PMID 26757712, 2016).
COVID-19 (3 papers, 2022 to 2024). A disease caused by infection with severe acute respiratory syndrome coronavirus 2. "Variants of IRF1, IFNAR2 and DR1 associated with lower COVID-19 severity increase type I IFN signalling in lymphoid cells by upregulating IRF1 and IFNAR2 or downregulating DR1, attesting to the importance of efficient IFN signalling for a favourable clinical outcome." (PMID 37558883, 2023). "Nevertheless, we identified cases (for example, DR1, OAS1-3, TOMM7, MUC20) in which selection or archaic introgression contributed to changes in both SARS-CoV-2 immune responses and COVID-19 outcome." (PMID 37558883, 2023). "On the other hand, 450 (22.96%) and 63 (41.18%) DEGs were downregulated (Down) in COVID-19 patients and recovered subjects, respectively, and of them, only 12 genes (i.e., MAFF, ARHGEF12, DCUN1D3, DR1, MT-CO1)." (PMID 36059456, 2022).
viral infection (3 papers, 2012 to 2025). "Simultaneously, the HLA-A*02:01- and HLA-A*11:01-restricted T cell epitope peptides predicted and selected using immunoinformatics were used to stimulate the HLA-A2/DR1 transgenic mice, HLA-A11/DR1 transgenic mice, and wild-type mice after viral infection." (PMID 40266241, 2025). "In order to confirm that these epitopes were truly processed and presented in the context of viral infection, we infected DR1+ (class 2 knockout [KO] C57BL/6) mice with X31, lab-adapted strain of IAV (H3N2) and measured ex vivo IFN-γ ELISpot responses." (PMID 32668259, 2020). "What also emerges from our analysis is the DR1 mouse as a potentially useful model to gain insights into regulation of the B cell response to viral infection of the respiratory tract." (PMID 22457834, 2012).
autoimmune disease (2 papers, 2017 to 2023). A disorder resulting from loss of function or tissue destruction of an organ or multiple organs, arising from humoral or cellular immune responses of the individual to their own tissue constituents. "Associations have also been made with retinal S-antigen and HLA B5, DR1, DR4, and patients with autoimmune disease." (PMID 29450389, 2017).
bladder cancer (2 papers, 2014 to 2017). "Oncomine database analysis revealed upregulation of DR1 in superficial and infiltrating bladder cancer samples, compared to normal bladder." (PMID 25135188, 2014). "We utilized Oncomine database of clinical samples, which showed overexpression of DR1 also in superficial and infiltrating bladder cancer." (PMID 25135188, 2014). "In addition, Oncomine database analysis for DR1 expression in bladder cancer revealed a statistically significant (P < 0.0001) upregulation of the gene in clinical samples of both superficial and infiltrating bladder cancer, when compared to normal bladder." (PMID 25135188, 2014). "Since hyperactivity of mutant RXRA was dependent on PPAR expression, we reasoned that no hyperactivity would be observed in the DR-1 luciferase reporter assay in a bladder cancer cell line with low endogenous expression of PPARs." (PMID 29143738, 2017).
Allergy (1 paper, 2019). An allergy is an immune response or reaction to substances that are usually not harmful. "Notably, neither 24 nor 48 hours of co‐incubation of MA::Art v 1 VNP, Art v 1::GPI VNP, empty VNP (10 μg/mL each), or rArt v 1 protein (1 μg/mL) with bone marrow‐derived dendritic cells (BMDC) of TCR/DR1 allergy mice upregulated CD40, CD80, CD86, or MHC class II expression, when compared to medium." (PMID 30035810, 2019).
atherosclerosis (1 paper, 2019). A disease characterized by the build-up of fatty material and calcium deposition in the arterial wall resulting in partial or complete occlusion of the arterial lumen. "The expression levels of key genes in the dopaminergic signaling pathway and the fluid shear stress and atherosclerosis pathway, including th, dr1, dr2, dat, mao, β-catenin, hsp90, calm, mek5, F-actin, and et-1, were analyzed." (PMID 31835337, 2019).
Chorea (1 paper, 2021). Chorea (Greek for 'dance') refers to widespread arrhythmic involuntary movements of a forcible, jerky and restless fashion. "The differential diagnosis of psychosis is very important, as psychosis can be also a symptom of a basal ganglia encephalitis with dopamine receptor 1 (DR1) and DR2 antibodies in Syndenham chorea and PANDAS." (PMID 34057596, 2021).
diabetes (1 paper, 2022). "After administration of dopamine 1-like receptors (DR1) agonist SKF38393 and exogenous H2S donor NaHS, the expression of CSE was increased and the change in proliferation-related proteins caused by diabetes was reversed." (PMID 35656112, 2022). "In order to further study the mechanism of DR1 and H2S, the mouse aortic smooth muscle cell line MOVAS was used to simulate diabetes in mice." (PMID 35656112, 2022).
Hydrocephalus (1 paper, 2022). Hydrocephalus is an active distension of the ventricular system of the brain resulting from inadequate passage of CSF from its point of production within the cerebral ventricles to its point of absorption into the systemic circulation. "These suggest that hydrocephalus might have also affected basal ganglia activity by reducing the action of dopamine on the direct pathway earlier than the indirect pathway since d and i-MSNs express principally DR1 and DR2 respectively." (PMID 36437472, 2022).
myocarditis (1 paper, 2020). Myocarditis is a condition that is characterized by inflammation of the heart muscle (myocardium). "In addition to allele associations, one HLA supertype, DR1, exhibited a significant association with decreased frequency of clozapine-induced myocarditis (OR < 1)." (PMID 32066683, 2020).
osteosarcoma (1 paper, 2019). A usually aggressive malignant bone-forming mesenchymal neoplasm, predominantly affecting adolescents and young adults. "In a different study, the same research group suggested that activation of DR1 induces osteosarcoma cell apoptosis via changes to the MAPK pathway." (PMID 31088504, 2019). "The Authors proposed DR1 as a novel target for the treatment of osteosarcoma." (PMID 31088504, 2019).
periodontal disease (1 paper, 2016). "Recent research has suggested that this same DR1 restriction element may also serve as a susceptibility allele for periodontal disease, providing a unique opportunity for use as an animal model that is perfectly suited for the analysis of linkages between the two disease processes." (PMID 27784339, 2016).
septicemia (1 paper, 2023). "As S. suis-induced septicemia often leads to organ failure, bacterial loads were also monitored in organs (liver, kidney, and spleen) at 72 h post-infection, when the blood bacterial load of HLA-A11/DR1 started to be significantly higher than that of WT group." (PMID 38035330, 2023).
Sjögren's syndrome (1 paper, 2024). "We found DR1 and DR14 to be associated with an increased risk of eye involvement in patients with Sjögren's syndrome." (PMID 39115243, 2024). "We found in our study that anti‐CCP seropositivity was associated with DR10 but found no such association with DR1 or DR4 in Sjögren's syndrome." (PMID 39115243, 2024).
squamous cell carcinoma (1 paper, 2014). A carcinoma arising from squamous epithelial cells. "DR1 was found to be significantly overexpressed in the SCaBER, which is a model of squamous cell carcinoma." (PMID 25135188, 2014). "Since SCaBER is a squamous cell carcinoma cell line, we wished to interrogate whether DR1 is overexpressed also in the urothelial carcinoma." (PMID 25135188, 2014).
Tinnitus (1 paper, 2020). Tinnitus is an auditory perception that can be described as the experience of sound, in the ear or in the head, in the absence of external acoustic stimulation. "So, it seemed that DR2/3 activation would suppress tinnitus, whereas DR1 activation would enhance tinnitus." (PMID 32249815, 2020).
uveal melanoma (1 paper, 2019). A melanoma derived from melanocytes of the uveal tract. "Collectively, our data indicate that Mel202/DR1/CD80 uveal melanoma vaccine cells maintain the activation of various subtypes of CD4+ T cells." (PMID 30956760, 2019). "Finally, Mel202/DR1/CD80 uveal melanoma vaccine cells expressed the intercellular adhesion molecule 1 (ICAM-1) that was pivotal for CD4+ T cell activation via lymphocyte function-associated antigen 1(LFA-1)." (PMID 30956760, 2019). "Therefore, the ICAM-1/LFA-1 interaction plays an important role in the activation of CD4+ T cells by Mel202/DR1/CD80 uveal melanoma vaccines." (PMID 30956760, 2019).
tumor (12 papers, 2008 to 2025). "More importantly, the combined HAGE/WT1 ImmunoBody® vaccine significantly delayed tumour growth in the B16/HHDII+/DR1+/HAGE+/WT1+ tumour model and prolonged mouse survival in the prophylactic setting in comparison to non-immunised control mice." (PMID 34262856, 2021). "H-2 KO/HLA-A2+-DR1+ transgenic mice were i.v. injected with 2 × 105 tumor cells expressing the entire human CD20 molecule (EL4-huCD20)." (PMID 31494742, 2019). "More importantly, the peptide DR-1 can induce cytotoxicity of CD4 T cells against tumor cells highly expressing cyclin D1 in the context of HLA-DR.B1 molecules." (PMID 19707583, 2009). "The use of H-2 KO/HLA-A2+-DR1+ transgenic mice inoculated with EL4-huCD20 tumor cells enables the detection of mouse T cell responses directed against human CD20, a xenogeneic antigen in this setting, in contrast to the assays with human samples in which autologous CD20-derived peptides are used." (PMID 31494742, 2019). "Moreover, the tumour overexpressed the receptors DR1 and DR5 (50 and 21 FC respectively)." (PMID 28692683, 2017). "We therefore tested if the DR-1 and D1-1 peptide-stimulated CD3 T cells were cytotoxic to tumor cells highly expressing cyclin D1." (PMID 19707583, 2009). "Notably, miR-181b-5p and miR-877-5p acted as negative regulators of tumor-suppressor genes (e.g., HEY2, MCL2, HAND2), while miR-204-5p and miR-143-3p appeared to indirectly target oncogenes (e.g., RAB10, DR1, PTBP3, NCBP1)." (PMID 41009685, 2025). "To investigate if depletion of T-regs could enhance the recognition of naturally processed epitopes in tumor cells by CD4 T cells, we compared DR-1-specific response between CD4+CD25+ T cells and CD4+CD25-T cells from the same donors in the IFN-γ ELISPOT assay." (PMID 19707583, 2009).
infection (8 papers, 2010 to 2025). The state of being infected such as from the introduction of a foreign agent such as serum, vaccine, antigenic substance or organism. "We successfully constructed the CCHFV tecVLPs system and established a Huh7 cell infection model and HLA-A11/DR1 mouse infection model." (PMID 37026060, 2023). "The earlier finding suggests a pro-recruitment propensity of HLA-A11/DR1 after infection, while the role of HLA-A11/DR1 in neutrophil bactericidal capacity remains unknown." (PMID 38035330, 2023). "MCP3 was identify as an important chemokine which attract macrophages and monocytes to further amplify inflammatory processes and contribute to disease progression, in our study a higher level of MCP-3 was significantly observed in HLA-A11/DR1 group at 12 h post-infection." (PMID 38035330, 2023). "Notably, lower levels of IL-10 were observed in the humanized mice, suggesting that HLA-A11/DR1 may extend the presence of pro-inflammatory factors and interfere with IL-10 secretion during infection." (PMID 38035330, 2023). "To study the pathological changes in lung tissue of HLA-A11/DR1 transgenic mice after SARS-CoV-2 infection, we fixed and sectioned the lung tissues of mice at 3 days post-infection (dpi) for histopathological examination." (PMID 40333292, 2025). "At 12 h and 144 h post-infection, a higher percentage of CD4+ CD25+ and CD4+ CD25+ Foxp3 cells were observed in the HLA-A11/DR1 Tg group." (PMID 38035330, 2023). "Additionally, our examination of bacterial clearance rates suggests that HLA-A11/DR1 primarily influences cell recruitment and mitochondrial reactive oxygen species (ROS) production, which affects the bacterial killing capacity of macrophages in the late stage of infection." (PMID 38035330, 2023). "DR1, grouped into one environmental clade and are not involved in serious human infection." (PMID 25881070, 2015).
cancer (3 papers, 2009 to 2023). A tumor composed of atypical neoplastic, often pleomorphic cells that invade other tissues. "However, only DR-1-stimulated CD4 or CD3 T cells possessed cytotoxicity against peptide-pulsed autologous DCs and a cancer cell line, that expresses a high level of cyclin D1." (PMID 19707583, 2009).
DR1 also shares sentences with these, for which no sentence is quoted: influenza (3 papers); acute hepatitis C (1); anemia (1); Chlamydia infections (1); chronic hepatitis C (1); chronic periodontitis (1); developmental verbal dyspraxia (1); follicular lymphoma (1); leukopenia (1); malaria (1); multiple sclerosis (1); myeloid malignancies (1); neuroblastoma (1); psoriasis (1); psychosis (1); Thrombocytopenia (1); urothelial carcinoma (1).